IL1B (interleukin 1 beta)
Diseases named in the same sentence as IL1B in open-access papers (continued):
Sharing a sentence is not in itself a finding about the gene and the disease.
pancreatic cancer (continued). "The microbial dysbiosis could induce TLR4-NLRP3 signaling, resulting in an enhanced secretion of IL-1β by pancreatic tumor cells." (PMID 35741028, 2022). "In this manner, IL-1β has attracted attention as another therapeutic target for pancreatic cancer." (PMID 36140220, 2022). "IL-1β also promotes immune suppression in pancreatic cancer." (PMID 35626430, 2022). "Thus, the inhibition of NETs/ IL‐1β/EGFR signalling is a new hope for targeted therapy of pancreatic cancer." (PMID 33955688, 2021). "Particularly, some cytokines implicated in cancer-associated muscle wasting such as IL-6 and IL-1β are not elevated, consistent to a previous study in pancreatic cancer patients." (PMID 34950660, 2021). "Taken together, these results showed that IL1β secreted from pancreatic cancer cells could activate NF-κB signaling in SCs via IL1R1 to promote pro-inflammatory cytokine production." (PMID 32308766, 2020). "In support of this hypothesis, we previously reported mRNA IL-1β expression in both the pancreatic tumor epithelial and stromal compartments, and IL-1β staining within the stroma mainly in association with CD163 positive TAMs." (PMID 30760333, 2019). "Moreover, patients with pancreatic cancer with high IL-6 and IL-1β levels display low overall and recurrence-free survival after gemcitabine treatment." (PMID 28928376, 2017). "In pancreatic cancer cell lines, IL-1β promotes cell growth and resistance to chemotherapy." (PMID 26894969, 2016). "Interestingly, all but 3 (FGF-2, RANTES and IL1β) of the 23 mediators that emerged as significant when comparing pancreatic cancer to nonmalignant tissue also emerged as significant when comparing pancreatic cancer to pancreatitis." (PMID 26498838, 2015). "Furthermore, additional studies have shown that NETs induce migration, invasion, and EMT (epithelial–mesenchymal transition) of pancreatic cancer cells in an IL-1b/EGFR/ERK-dependent manner, which could potentially be utilized for therapy." (PMID 40427186, 2025). "Interestingly, analysis of 60 patients with advanced pancreatic cancer who received gemcitabine showed that the serum levels of IL1β and IL6 were poor prognostic factors for overall survival and the levels of these cytokines predicted the efficacy of gemcitabine in this population." (PMID 37772994, 2023). "Similarly, secreted IL-1β and the constitutively expressed IL-1 receptor associated kinase 4 (IRAK4) induce the activation of the NF-κB pathway both in CAFs and pancreatic cancer cells, alleviating the cytotoxicity of gemcitabine in pancreatic tumors." (PMID 33732706, 2021). "Thus, inflammasome inhibition may suppress the pancreatic cancer cell growth via downregulation of IL-1β and IL-18." (PMID 32974137, 2020). "In the present study, we reported the detection of IL-1β-producing M2 polarised macrophages in pancreatic cancer, and revealed that their pro-inflammatory function could be further enhanced by IgG via crosstalk between the TLR4-TRIF and FcγRI/III-SYK signalling pathways." (PMID 31588122, 2019). "In this model, pancreatic tumor cells release TNF-α and IL-1β proinflammatory cytokines, which had been previously reported, stimulating CAFs to secrete TSLP." (PMID 40453074, 2025). "In pancreatic cancer, CAFs have been found to secrete thymic stromal lymphopoietin (TSLP) following activation by tumor-derived TNF-α and IL-1β." (PMID 40453074, 2025). "In pancreatic cancer, ATP6AP1 depletion suppresses lysosomal acidification and IL-1β secretion, suggesting its potential role in modulating pyroptosis-related pathways and TME dynamics." (PMID 40281381, 2025). "IL1B+ macrophages were found colocalizing with EMT-enriched tumors cells at the invasive edge in kidney cancer, whereas in pancreatic cancer they have been shown to induce inflammatory reprogramming of cancer cells." (PMID 40393458, 2025).
pancreatic cancer (continued). "Conversely, in prostate cancer, pancreatic cancer, and HCC, IL-1β has been found to accelerate tumor progression by inducing immunosuppression and promoting inflammation and metastasis." (PMID 39744568, 2025). "Expression of IL33 and other IRF3 target genes, TNF, IL1B, and CXCL10, were highly upregulated in pancreatic cancer compared to the normal pancreas in a large collection of samples represented in TCGA and GTEx databases." (PMID 38816352, 2024). "This loop between IL-1β+ TAMs and PDAC shapes the tumour-intrinsic IL-1β response program in hypoxic regions of the pancreatic tumours, resulting in early tumorigenesis." (PMID 39430099, 2024). "Tumor cell-derived IL-1β establishes an immunosuppressive milieu characterized by M2-like macrophages, MDSC, Th17 cells, and CD1dhi CD5+ regulatory B cells in pancreatic cancer." (PMID 36932407, 2023). "Of note, pancreatic carcinoma cells constitutively express LIF and its heterodimer receptor (LIFR and gp130), and TNFα, IL1β or LIF itself enhanced the expression of LIF mRNA." (PMID 35565186, 2022). "Interestingly, this axis may be a valuable therapeutic target to potentially circumvent chemoresistance in pancreatic cancer as targeting IRAK4 or IL-1β could render PDAC tumors less fibrotic and more sensitive to gemcitabine and, potentially, other chemotherapeutic agents." (PMID 34646829, 2021). "In general, NETs promote pancreatic cancer EMT, migration and invasion dependent on EGFR/ERK pathway through IL‐1β, providing new thoughts on the interaction between NETs and pancreatic cancer cells." (PMID 33955688, 2021). "On the other hand, in resected pancreatic cancer patients, CCL2 is an independent favorable prognostic factor with indirect effects on pancreatic cancer cell growth via cytokines, such as IL1B." (PMID 32429318, 2020). "High levels of cytokines IL-1β, IL-6, IL-8, IL-10, TGF-β, and TNF-α are observed in patients with pancreatic cancer compared to healthy patients." (PMID 32174830, 2020). "In our study, we evaluated the changes in several important pro-inflammatory cytokines in pancreatic cancer, including TNF-α, IL-6, and IL-1β." (PMID 33634030, 2020). "Importantly, we found that a relevant molecule driving IL-1β secretion by macrophages is the inflammasome adaptor ASC (apoptosis-associated speck-like protein containing a caspase recruitment domain), which can be released by ASC expressing pancreatic cancer cells." (PMID 30760333, 2019). "We do not exclude that PDAC cells release additional alarmins/molecules helping to drive IL-1β production and inflammasome activation in macrophages, as in the case of methylated ASC pancreatic cancer cells." (PMID 30760333, 2019). "Our findings indicate that tumor released IL-1α and IL-1β and ASC are key regulators of TSLP secretion by CAFs and their targeting should ultimately dampen Th2 inflammation and improve overall survival in pancreatic cancer." (PMID 30760333, 2019). "IL-1β induces MMP-9 expression in other cell lines and enhances the invasiveness of human pancreatic cancer cells." (PMID 23737761, 2013). "Our results demonstrate that the proadhesion molecules E-selectin, ICAM-1, and VCAM-1, the pro-inflammatory IL-1β and MCP-1, and the prometastasis gene MMP-9 are BCL-6-regulated genes in human pancreatic cancer cells." (PMID 23737761, 2013). "Similarly, in pancreatic cancer, CAFs facilitate a shift toward a Th2 immune response through the secretion of TSLP in response to TNF-α and IL-1β, which polarizes DCs toward an immunosuppressive phenotype." (PMID 40453074, 2025). "More broadly, our study highlights a critical facet of the tumor-TAM interaction: while proinflammatory cytokines IL-1β and TNF-α promote tumor progression, they also create a metabolic vulnerability in pancreatic cancer cells by enforcing reliance on the de novo pyrimidine synthesis pathway." (PMID 41243973, 2025).
pancreatic cancer (continued). "The activation of the IL-1β/epidermal growth factor receptor (EGFR)/extracellular-signal-regulated kinase (ERK) pathway is prompted by NETs, resulting in the promotion of migration, invasion, and EMT of pancreatic cancer cells." (PMID 38835055, 2024). "We previously showed that tumor organoids from non-cachectic pancreatic cancer patients expressed higher IL-1β mRNA levels compared to tumor organoids from cachectic patients." (PMID 38339292, 2024). "CM from the pancreatic tumor organoids of cachectic patients did not affect IL-1β, IL-6, IL-8, MCP-1, or Atrogin-1 expression." (PMID 38339292, 2024). "In line with this, we previously showed that pancreatic tumor organoids from cachectic and non-cachectic pancreatic cancer patients expressed variable levels of known cachexia-associated cytokines, including IL-6, TNF-α, IL-8, IL-1α, IL-1β, Mcp-1, and LIF." (PMID 38339292, 2024). "Given that IL-1β-mediated degradation of Regnase-1 promoted PDAC in our study, Regnase-1 stabilizing agents could be used to suppress pancreatic cancer progression." (PMID 37814340, 2023). "Taken together, our findings suggested that IL-1β-induced Regnase-1 downregulation may produce a variety of cytokines/chemokines important for the intratumor MDSC increase, promoting pancreatic tumors." (PMID 37814340, 2023). "Overexpression of IFI-16 in pancreatic cancer cells induces the maturation, infiltration, and proliferation of TAM in the tumor microenvironment by activating inflammasomes and therefore increasing the release of IL-1β." (PMID 35739593, 2022). "This indicates that in NACT-treated ovarian cancer, TNF/IL6 drives the iCAF phenotype rather than IL1B, which has a leading role in promoting the iCAF phenotype in pancreatic cancer." (PMID 35196078, 2022). "And inhibition of IL‐1β/EGFR/ERK pathway could effectively inhibit NETs‐induced migration, invasion and EMT of pancreatic cancer." (PMID 33955688, 2021). "It has also been shown that IL‐1β plays important roles in EMT42 and pancreatic cancer progression." (PMID 33955688, 2021). "The pleiotropic IL1β was decreased in direct but not separated co-cultures, and the cytokine is involved in detrimental pancreatic cancer desmoplasia and immunosuppression." (PMID 34064000, 2021). "Importantly, we found that pancreatic cancer cells release alarmins, among which ASC, able to induce IL-1β secretion in macrophages." (PMID 30760333, 2019). "Recent work further showed elevated IL-8 in cachectic versus non-cachectic resected and locally advanced pancreatic cancer patients, which was not the case for IL-6, IL-1β, or TNF-α." (PMID 31769424, 2019). "Furthermore, in pancreatic cancer, L1CAM promotes, via α5-integrin para- or autocrine signaling of IL1β, which induces iNOS activation and NOS secretion, leading to the inhibition of caspase 3 and 7 activity." (PMID 31455004, 2019). "Cancer cell–produced IL-1β was previously shown to induce TSLP in breast or pancreatic cancers, but ex vivo culture of epidermis from WT mice with IL-1β did not induce TSLP production, suggesting that, at least on its own, IL-1β does not induce the expression of epidermal TSLP." (PMID 36107619, 2022). "And then, we co-cultured TNFSF9-knockdown pancreatic cancer cells with U937-derived macrophages and found that compared with the sh-NC group, the mRNA levels of M1-type markers (TNF-α and IL-8) in sh-TNFSF9-1 and sh -TNFSF9-2 groups were increased and the mRNA levels of IL-1β were decreased." (PMID 34517345, 2021). "These cytokines, such as interleukin-1β (IL-1β), IL-6, IL-8, IL-10, tumor necrosis factor-α (TNF-α), and transforming growth factor-β (TGF-β) are potential prognostic biomarkers as well as targets in the pathogenesis of pancreatic cancer and in peripheral nerve injury." (PMID 32174830, 2020).
pancreatic cancer (continued). "In addition, L1CAM-integrin binding was shown to induce interleukin (IL)-1β production in pancreatic cancers, and IL-1β was reported to transactivate EGFR in OSCC, implying that the interaction of L1CAM and integrin might promote EGFR activation via inducing IL-1β upregulation in OSCC." (PMID 38263290, 2024). "Our results show that P2X7R (~20-fold), its key inflammasome components: caspase-1 (15-fold), IL-1β (~45-fold), and in addition to (data not shown) IL-18 (~35-fold), IL-33 (~93 folds), TNF-α (~13-fold) and COX-2 (~41-fold) are increased in pancreatic tumors compared to normal pancreas." (PMID 29228654, 2017).
renal fibrosis (124 papers, 2011 to 2026). A final common manifestation of a wide variety of chronic kidney diseases characterized by glomerulosclerosis and tubulointerstitial fibrosis. "CD248 is also identified as a pivotal stromal cell marker in renal allograft rejection, associated with HIF-1α and IL-1β pathways (also two pivotal pathways in renal fibrosis of DN)." (PMID 41382249, 2025). "Additionally, in PTECs, the upregulation of fascin-1 expression caused by IL-1β leads to renal fibrosis." (PMID 38260142, 2023). "Confirming our dose range experiments, X203 reduced AKI-induced loss of kidney mass, limited renal fibrosis, and improved renal function while lowering inflammatory (Tnfα, Il6, Ccl2, Ccl5, Il1β), fibrosis (Col1a1, Col1a2, Col3a1, Fn1, Acta2) and tubular damage (Kim1, Ngal) markers." (PMID 36470928, 2022). "Renal fibrosis results from reduced endothelial proliferation following alterations in local expression of both angiogenic and antiangiogenic factors, and this imbalance is mediated by macrophage-associated cytokines, such as interleukin 1 beta, and vasoactive mediators." (PMID 28870174, 2017). "It significantly reduced cardiac and renal fibrosis and suppressed the expression of pro-inflammatory (IL-1β, TNF-α), pro-fibrotic (Col1A1, α-SMA), and cardiac stress (BNP, ET-1, ANF) markers." (PMID 41596359, 2026). "Consistently, the tubular injury and renal fibrosis scores were lower in LIPUS-treated CKD mice with IL-1β stimulation, compared with those in diseased renal tissue without LIPUS treatment." (PMID 40729113, 2025). "Injured renal tubular epithelial cells secrete multiple cytokines, including TGF-β, Wnt, and IL-1β, to recruit immune cells and activate myofibroblasts, resulting in the progression of renal fibrosis." (PMID 40758676, 2025). "In diabetic nephropathy models, both in vivo and in vitro, MCC950 attenuates glomerular basement membrane thickening, podocyte injury, and renal fibrosis by suppressing the NLRP3/caspase-1/IL-1β signaling axis." (PMID 41357229, 2025). "Inhibition of acyl-CoA synthetase short chain family member 2 (ACSS2) suppresses H3 K9 crotonylation-mediated IL-1β expression, thereby alleviating IL-1β-dependent macrophage activation and tubular cell senescence, and consequently delaying renal fibrosis." (PMID 40478495, 2025). "To further verify the role of IL-1R in the therapeutic efficacy of LIPUS on renal fibrosis and tubular injury, we subjected mice to IL-1β stimulation and LIPUS." (PMID 40729113, 2025). "Deficiency of CHOP can ameliorate renal ischemia-reperfusion injury in mice, and prevents UUO-induced renal fibrosis by attenuating fibrotic signals derived from HMGB1/TLR4/NF-κB/IL-1β signaling." (PMID 41280890, 2025). "Although anti-IL-1β IgG can help treat renal fibrosis, monoclonal antibodies are seemed to be prohibitively expensive for CKD patients who require long-term treatment." (PMID 38615014, 2024). "Anti-IL-1β IgG dramatically improved renal fibrosis in UUO mice, as demonstrated by Masson’s trichrome staining and the decreased mRNA and protein expression of kidney fibrotic markers." (PMID 38615014, 2024). "Future studies must explore the potential link of Mon effects on autophagy with NLRP3, ROS, IL-1β, and improvement in renal fibrosis to understand its renoprotective impact against DN better." (PMID 37498374, 2024). "Activated IL-1β stimulates the accumulation of c-Myc and upregulates the c-Myc target gene, which contributes to renal fibrosis in renal aging." (PMID 39199133, 2024). "The mRNA expression of proinflammatory cytokines (TNF-α and IL-1β) and renal fibrosis markers (tumor growth factor [TGF]-β1 and connective tissue growth factor) were also consistently upregulated in the renal cortex of 24-week-old db/db mice." (PMID 38016515, 2023). "M1 macrophages can produce pro-inflammatory cytokines such as TNF-α, IL-1β, and IL-6, promoting the progression of renal fibrosis." (PMID 37861543, 2023).